DLL4 (delta like canonical Notch ligand 4)
Diseases named in the same sentence as DLL4 in open-access papers (continued):
Sharing a sentence is not in itself a finding about the gene and the disease.
tumor (continued). "This is illustrated for example by studies on tumor initiation (Notch1; Notch3), stem cell control (Notch1; Notch4; Jag1; Jag2; DLL1), angiogenesis (Notch1; DLL4) invasion and metastasis in remote organs (Notch1; Notch2; Jag1; DLL1)." (PMID 32605277, 2020). "HD105, a bispecific antibody, effectively inhibits angiogenesis and tumor growth by specifically blocking the VEGF/VEGFR2 and Dll4/Notch1 signaling pathways." (PMID 28881855, 2017). "To confirm our observation in HCC cell lines, we investigated the expression level of Notch1, Jagged1 and Dll4 in HBV-infected HCC specimens, comparing between tumor and non-tumor lesions." (PMID 26766040, 2016). "Extensive tumor necrosis and non-functional angiogenesis were observed in RCC tumors in response to Dll4 blockade." (PMID 25393540, 2014). "Significant (p<0.05) cell death was observed in tumours treated with USMB+XRT+Dll4 mAb, while a non-significant increase in cell death was observed for animals treated with radiation combined with Dll4 mAb." (PMID 24736631, 2014). "An anti-DLL4 antibody, OMP-21M18, was found to have anti-tumor activity in patient-derived xenograft models independent of any effect on angiogenesis." (PMID 21831306, 2011). "The rationale for this is not new; DLL4, like VEGF, is targeted to disrupt tumor angiogenesis, with an intent to prevent further tumor growth and/or improve delivery of alternative therapeutics through normalized tumor vasculature." (PMID 33912195, 2021). "Similarly, given that high expression of Dll4 in OC correlated with non-responsiveness to anti-VEGF therapy, it has been proposed to also block both pathways in this tumor type." (PMID 35582386, 2021). "However the reduction of DLL4 expression in vessels was not prominent in mDLL4-tumours treated with DBZ, bevacizumab or combination (V, VIII and XI), suggesting the enhanced expression of endogenous DLL4 by mDLL4 was more resistant to reversal by DBZ." (PMID 28445154, 2017). "Unlike DLL4, JAG1 expression in ECs has been shown to have proangiogenic functions; to antagonize DLL4/Notch signaling but also to promote vascular maturation and so to aid tumor growth." (PMID 28533486, 2017). "Interestingly, despite clear blood vessel remodeling, Dll4 blockade did not have activity as a single agent in this sunitinib resistant PDX model, but it potentiated the anti-tumor effect of ziv-aflibercept by inducing tumor regression." (PMID 25393540, 2014). "For example, in pre-clinical models, blockade of the angiogenic ligand Dll4 results in increased MVD and endothelial cell marker genes (data not shown), but inhibits tumor growth, thus clearly showing that MVD changes are not predictive of anti-angiogenic treatment efficacy." (PMID 23238831, 2013). "DLL4 activates Notch signaling in the stalk ECs to inhibit sprouting angiogenesis and results in fewer but larger vessels, whereas JAG1 mainly increases sprouting angiogenesis and enhances the amount rather than the size of vessels by signaling to tumor cells and ECs." (PMID 32046779, 2020). "Next, to test whether the role of Dll4-expressing BM-VPC was essential to tumor angiogenesis, we developed an in vivo approach in which we reconstituted NOD-SCID mice BM with BM-VPC obtained from Dll4+/− (heterozygous, with reduced Dll4 levels) or from WT (normal Dll4 levels) mice." (PMID 21483741, 2011). "A role for Notch signaling in tumor angiogenesis was originally hypothesized from the observation that VEGF induced Dll4 in the angiogenic endothelium of tumor xenografts and blocking Dll4 functions resulted in dysregulated non-productive angiogenesis." (PMID 21349159, 2011).
cancer (109 papers, 2009 to 2025). A tumor composed of atypical neoplastic, often pleomorphic cells that invade other tissues. "pySCENIC transcription factor analysis of single-cell transcriptomes revealed that NANOS1, a transcription factor, was significantly enriched in TTN-deficient cancer cells with high DLL4 expression." (PMID 41326912, 2025). "And the expression level of DLL4 was significantly suppressed in TTN-deficient cancer cells after NANOS1 knockdown." (PMID 41326912, 2025). "DLL4 monoclonal antibodies, which were associated with PH in cancer patients, have been recently shown to cause pulmonary vascular remodeling and PH in mice through the inhibition of endothelial NOTCH1 signaling." (PMID 38903104, 2024). "When activated in cancer cells, members of the Notch family, such as Notch1 and its ligands Dll4 and Jagged1, are linked to proliferation, survival, and progression." (PMID 35480877, 2022). "Particularly, sequencing Notch gene mutations, including those of Dll4, have been detected in many types of cancers portraying information on the growth of particular gynecological types of tumors." (PMID 35406423, 2022). "The connection between Dll4 appearance level and the cancer stem cell associated protein Nestin (an angiogenesis indicator of multiplying endothelial cells in colorectal tumor vessels) was also analyzed." (PMID 35406423, 2022). "In this study we show that a bona fide IRES element is present in the 5′-UTR of DLL4 mRNA encoding the DLL4 protein that regulates angiogenesis during development, but also in pathological conditions, such as cancer." (PMID 30691003, 2019). "Recently, hepatic SD has also been associated with anti-delta like 4 (DLL4) cancer therapies targeting the NOTCH pathway." (PMID 29879147, 2018). "Our results indicate that DLL4 expression is associated with TNM stage and cancer metastasis, with high amounts of DLL4 leading to poor outcome." (PMID 27891816, 2017). "The association between DLL4 expression level and the cancer stem cell related protein Nestin was also analyzed." (PMID 27891816, 2017). "Considering that cancer stem cells have proven to be implicated in the progression of many cancer types, any impact from Dll4 could lead to the alteration of cancer development." (PMID 35406423, 2022). "Dll4 is associated with the formation of leader cells during collective cancer invasion." (PMID 35480877, 2022). "Finally, endothelial expression of DLL4 was demonstrated to be significantly associated with VEGF-A in many cancers including glioma, colon, nasopharyngeal and lung cancers." (PMID 30691003, 2019). "We found a significant correlation between cancerous and stromal DLL4 expression; thus, DLL4 may be associated with lymphatic metastasis, consistent with what has been shown in other cancers." (PMID 23898884, 2013). "The modulation of the Notch ligands Dll4 and Jagged1, which are associated with leader cells, suggest Nrf2 may modify the formation of leader cells during collective cancer migration." (PMID 35480877, 2022). "We next investigated the relationship between the proportion of DLL4+ cancer cells in TNBC and the subpopulation of MCT4+ MDSCs obtained via reverse convolution of the same single-cell sequencing in the TME." (PMID 41326912, 2025). "Expression level data of Notch1-4 and DLL4 in cell lines were downloaded from the CCLE (cancer cell line encyclopedia) database." (PMID 39951484, 2025). "Based on immunohistochemical analysis, DLL4, a ligand of the Notch signaling pathway, exhibited significant upregulation in cancer tissues compared to adjacent tissues(p<0.05)." (PMID 38650927, 2024). "Our clinical sample analysis revealed that the expression of Notch pathway receptor Notch1 and ligand DLL4 was significantly higher in HCC tissues compared to para-cancer tissues." (PMID 38650927, 2024).
cancer (continued). "Molecules targeting Notch signaling including the γ-secretase inhibitors and anti-DLL-4 antibody, which are currently being investigated in clinical trials for cancer, can be promising candidates for antiplatelet and antithrombotic therapies." (PMID 38172855, 2024). "Among the genes downregulated upon GPR81 KD, we choose DLL4 for further analysis in light of its potent downregulation and the importance of DLL4-Notch signaling in cancer." (PMID 37993804, 2023). "We further show that this plays a key role in the effects of the receptor on cancer cell 3D growth and invasiveness, likely in part through regulation of Notch ligand DLL4." (PMID 37993804, 2023). "NIR imaging with ICG can noninvasively assess Dll4 expression levels in tumors and aid in effective decision making for cancer therapy." (PMID 36900252, 2023). "Delta like canonical notch ligand 4 (Dll4) expression levels in tumors are known to affect the efficacy of cancer therapies." (PMID 36900252, 2023). "NOTCH also plays an essential role in coordinating vessel development and maintenance 94 and cancer-related neoangiogenesis, in which the latter is mediated through the ligand DLL4." (PMID 35673577, 2022). "The precise dynamics acting between Dll4 and Jagged1 and its functional implications in cancer invasion should be further investigated." (PMID 35480877, 2022). "The current research article examines the background theory that implies the ability of Dll4 in the development of endometrial and other cancer types, and the probable therapeutic results of Dll4 inhibition." (PMID 35406423, 2022). "Administration of anti-human Dll4 reserved the administration of Notch target genes reducing proliferation of cancer cells, reduced cancer stem cell frequency, and deregulated angiogenesis by aiming at Dll4 in the vasculature." (PMID 35406423, 2022). "Dll4 is expressed in cancer cells and activates Notch1 signaling in an autocrine manner, while Jag1 is expressed in the neighboring HSCs and activates Notch2 signaling in adjacent cancer cells." (PMID 35064244, 2022). "HIF-2α increases the expression of DLL4 at the transcriptional level by binding directly to site 3 of the DLL4 promoter region, which then activates Notch1 signals, causing downstream secretion of MMP-9 for increased cancer cell migration." (PMID 35385679, 2022). "ER+ BC cells grown in coculture with DLL4+-HMVECs had higher levels of gene expression of cancer stemness-related genes (CD44, ALDH1A1, KLF4, and CD36) and PKD-1, as compared to ER+ BC cells grown in monoculture." (PMID 34168243, 2021). "Although CCNC loss of function mutations have been reported in some patients with T-ALL 23, the involvement of membrane-bound DLL4 in cancer cells remained elusive until our present proof of concept study showing DLL4 involvement in the human disease." (PMID 33408769, 2021). "This can be blocked by recombinant antibodies targeting the DLL4 protein at the cell surface of cancer and/or stromal cells within these tumors, or possibly the endothelial cells in these tumors that also express DLL4." (PMID 33430387, 2021). "DLL4/Notch inhibition is also known to reduce the number of cancer stem cells (CSCs), which are an important cancer cell population responsible for malignancy." (PMID 33383646, 2020). "ABL001 (NOV1501/TR009), a bispecific antibody targeting VEGF and DLL4, is being developed as an anti-angiogenic cancer therapeutic that strengthens the effects of VEGF inhibitors and eventually overcomes resistance to anti-VEGF therapy." (PMID 33383646, 2020). "Applying the same principle in vivo revealed that intracranial xenografts grew smaller when the initial inoculum included endothelial cells depleted for Dll4 or Jagged1, due to a concomitant reduction in cancer stem-like cells." (PMID 33198378, 2020). "A simultaneous blockade of VEGF/VEGFR and DLL4/Notch signaling pathways leads to more potent anti-cancer effects by synergistic anti-angiogenic mechanisms in xenograft models." (PMID 33383646, 2020).
cancer (continued). "Targeting DLL-4, either via ionizing radiation or deletion of the gene encoding DLL-4, has shown to slow the progression of GBM cancer cell lines by decreasing angiogenesis." (PMID 35582224, 2020). "The activated TF AHR can upregulate the expression of target gene DLL4 and activate the Notch signaling pathway, which can lead to tube formation in cancer cells, increase blood vessel branching, reduce pericyte recruitment, and reduce fibronectin expression." (PMID 31126066, 2019). "Blocking antibodies against Dll4, Notch1, Notch2, or Notch3 are already being tested in phase I clinical trials in cancer patients." (PMID 31191522, 2019). "The VEGF/Dll4/Notch pathway also functions in cancer angiogenesis, where changes in the expression levels of signaling molecules, including Notch ligands Dll4 and Jag1, lead to altered morphological features of the vascular endothelium." (PMID 29996493, 2018). "Reports indicate that NOTCH-3, JAG-1, and DLL-4 are among the most altered notch signaling genes in cancer." (PMID 26762567, 2016). "This study is an attempt to contribute to the rational design of potent clinical therapeutics by characterizing DLL4 protein expression in human cancer." (PMID 27542210, 2016). "Defining the context of DLL4 expression is critical to our understanding of potential treatment options available to cancer patients." (PMID 27542210, 2016). "These efforts have not been very successful and raise concerns for long-term treatment of cancer using DLL4 and Notch inhibitors." (PMID 27542210, 2016). "In fact, γ-secretase inhibitors or anti-Dll4/anti-Notch biologics are currently being evaluated in open clinical trials for cancer therapy." (PMID 26755662, 2016). "This has prompted the development of anti-DLL4 antibody and gamma secretase inhibitors as therapeutic agents for cancer patients." (PMID 27542210, 2016). "Together, our findings demonstrate potential utility of manipulating miR-27b levels in cardiovascular disease and cancer and confirm its targets as Dll4/Notch axis, PPARγ and its downstream effectors." (PMID 26161255, 2015). "Studies have also demonstrated the potential of Dll4 blockade in combination with other cancer therapies." (PMID 24736631, 2014). "DLL4, a predominantly endothelial specific gene, has also been reported to be expressed on cancer stem cells." (PMID 23990866, 2013). "Because of the importance of Notch signaling in stem cell biology, DLL4 has been investigated for its role in the maintenance and proliferation of cancer stem cells (CSC)." (PMID 21831306, 2011). "Anti-DLL4 attacks cancers through two distinct mechanisms, an anti-angiogenic effect and a reduction of CSCs, each fundamental for malignant tumor growth." (PMID 21831306, 2011). "The characterisation of Dll4 protein expression in human cancer is important for the rational design of clinical trials to test the safety and activity of anti-Dll4 therapy." (PMID 19844231, 2009). "The expression of Dll4 was only rarely observed in the endothelial lining of large vessels around or into which cancer cells had invaded." (PMID 19844231, 2009). "Similar to Jagged1 and 2, Dll4 expression was also higher in cancer, with ~53% of cancer cases displaying higher intensities of staining (3+ and 4+) for Dll4, while only 25% of normal cases displayed such high intensity staining." (PMID 20030805, 2009). "With the discovery that DLL4+ Mo-LCs most potently activated T cells among the monocyte-derived cells, targeting DLL4+ Mo-LCs may offer a promising therapeutic strategy such as in cancer treatment." (PMID 40018044, 2025). "Dll4 was expressed in cancer cells and engaged Notch1 signalling in an autocrine way, whereas Jag1 was expressed in neighbouring hepatic stellate cells and engaged Notch2 signalling in neighbouring cancer cells." (PMID 40052152, 2025).
cancer (continued). "DLL4 and NOTCH4 have been investigated for their roles in promoting metastasis and cancer stem cell activities, and their downregulation has been linked to a reduced metastatic burden and the inhibition of cancer stem cells." (PMID 38612588, 2024). "Several drugs targeting Notch signaling including γ-secretase inhibitors (such as RO4929097) and anti-DLL-4 antibodies (such as demcizumab and enoticumab) are currently under clinical trials for different cancers as monotherapy or in combination with other treatments." (PMID 38172855, 2024). "Human anti-DLL4 antibodies have been reported for cancer treatment." (PMID 36900252, 2023). "DLL4 blockade has measurable antitumor effects in animal models of various cancers 99,100." (PMID 35673577, 2022). "Non-canonical activation of the NOTCH1 receptor plays an important role in cancer and could explain the weak effect of y-secretase inhibition and DLL4 treatment." (PMID 35205828, 2022). "Moreover, DLL4 monoclonal antibodies are designed against cancers through disruption in their angiogenesis, because DLL4 is a Notch ligand involved in the process of angiogenesis." (PMID 36581900, 2022). "A third option to explain the effects of Dll4 knock-down may relate to the inhibition of neo-angiogenesis and thus reduced access to the vasculature by cancer cells." (PMID 33430387, 2021). "Direct endothelial DLL4-mediated Notch activation in circulating BCSCs in the arteriolar niche could promote the survival and metastatic potential of cancer cells." (PMID 34168243, 2021). "Therefore, we predicted VEGFA, APLN, and AGT genes as paracrine effectors for the cancer-stroma interaction in KIRCs, whereas DLL4, APP, and TGFB1 genes to be potential autocrine effectors." (PMID 35079698, 2021). "The DLL4/Notch1/Akt pathway is principally related to angiogenesis because it regulates the proliferation and migration of ECs in both normal conditions and in malignancies." (PMID 34671243, 2021). "Several anti-DLL4 monoclonal antibodies have successfully demonstrated broad preclinical antitumor activity, with multiple anti-DLL4 molecules currently investigated as potential cancer therapeutics 33, 42, 66-68." (PMID 32373218, 2020). "Delta-like ligand 4 (DLL4) may be another possible mAb target for PDAC treatment since the DLL4 signalling pathway is important for PDAC cancer stem cell (CSC) survival." (PMID 32061257, 2020). "In addition, using a co-culture system of human brain microvascular endothelial cells with glioblastoma multiforme neurospheres increased cancer stem-like cells’ self-renewal dependent on endothelial Dll4 and Jagged1 function." (PMID 33198378, 2020). "We hypothesized that the Tg6F-mediated increase in Notch1 and Notch 2 with increased Dll4 and Dll1 expression in the jejunum in the cancer model might affect the immune cell repertoire." (PMID 29899427, 2018). "Studies using a xenografted model of CRC suggested that Dll4, besides promoting a dysfunctional vasculature, could have an additional role maintaining the proliferative cancer stem cells." (PMID 28086833, 2017). "Targeting Jagged1 or Dll4 in Notch signaling in human cancers may thus be a promising anti-angiogenic therapeutic approach." (PMID 28881855, 2017). "Moreover, a Dll4-specific antibody has been shown to inhibit angiogenesis and growth of cancer cells by reducing activation of Notch signaling." (PMID 28881855, 2017). "Hu and colleagues have found that combining Dll4-targeted siRNA with VEGF inhibition bevacizumab was more effective in inhibiting angiogenesis in preclinical models of cancer, and patients with tumors after treatment with anti-VEGF therapy had lower Dll4 expression." (PMID 28284219, 2017). "Endothelial specific Dll4 overexpression thus appears as a promising anti-angiogenic modality that might improve cancer control." (PMID 28288569, 2017). "In fact, Dll4 is one of the therapeutic target for cancer treatment." (PMID 26766040, 2016).